LGR5 (leucine rich repeat containing G protein-coupled receptor 5)
Diseases named in the same sentence as LGR5 in open-access papers (continued):
Sharing a sentence is not in itself a finding about the gene and the disease.
colorectal cancer (continued). "These functional difference in colorectal cancer cells may indicate the complexity of the pathway that influences LGR5 expression during EMT." (PMID 35123536, 2022). "ASCL2 and LGR5 are two important target genes of Wnt signaling in colorectal cancer." (PMID 35299743, 2022). "LGR5 is recognized as a cancer stem cell (CSC) marker for colorectal cancer." (PMID 35123536, 2022). "Meanwhile, leucine rich repeat-containing G protein-coupled receptor 5 (LGR5), a colorectal cancer stem cell marker, is correlated with TGFβ and Wnt signaling, which could increase cell proliferation, survival, and metastasis in colon cancer 12,21,22." (PMID 33767593, 2021). "Furthermore, it is widely known that colorectal CSCs are best studied in vitro using human LGR5(+) colorectal cancer cells." (PMID 33713277, 2021). "Recently, studies using mouse organoids of colorectal cancer showed that Lgr5– cancer cells can convert to Lgr5+ TPCs to reinitiate tumor growth, and this conversion may be essential for metastatic colonization." (PMID 34618689, 2021). "Varying levels of LGR5 expressions have been reported in 2D cultures of different human colorectal carcinoma cell lines, including the widely used Caco cells in mouse primary colonic epithelial cell lines, and, at very low levels, in pig IPEC-J2 intestinal epithelial cell lines." (PMID 34205481, 2021). "LGR5 expression is increased in colorectal carcinoma (CRC) compared to normal tissue." (PMID 33541282, 2021). "Van Rheenen and colleagues study Lgr5+ cancer stem cells during colorectal cancer metastasis." (PMID 32169167, 2020). "Lgr5+ cells have been frequently investigated as CSC in colorectal cancer." (PMID 32671503, 2020). "Moreover, recent studies have highlighted the importance of R-spondin, Lgr5, and RNF43 in different cancers types, including colorectal cancer, which harbor inactivating mutations on RNF43." (PMID 33126517, 2020). "We further investigated the anti-stem cell activity of salinomycin, 5-FU, and oxaliplatin in patient-derived TICs applying qPCR to analyze the mRNA expression of Lgr5, which is regarded as substantial contribution to the colorectal cancer stem cell hierarchy and to colorectal carcinogenesis." (PMID 30763370, 2019). "Furthermore, in human gastric and colorectal cancer tissues, Lgr5+ cancer cells have been shown to exhibit properties of cancer stem cells (CSCs) or cancer-initiating cells." (PMID 31417548, 2019). "Lgr5, a Wnt target gene, has been widely used as a marker of organ stem cells with self-renewal capacity, as well as an established biomarker of cancer stem cells (e.g., colorectal cancer and mammary tumors)." (PMID 31358061, 2019). "LGR5 is another target gene of the WNT pathway as well as a marker of colorectal carcinoma CSCs." (PMID 31921125, 2019). "Lgr-5 plays an active role in pathogenesis of colorectal cancer, and the Lgr5 expression is closely related to tumorigenesis, 5-fluorouracil resistance and recurrence of colorectal cancer." (PMID 30279970, 2018). "LGR5 was shown to be capable of association with TGF-β receptors and its activation by R-spondin ligands determines the activation of LGR5 and the concomitant activation of TGF-βRII; furthermore, in colorectal cancer specimens, LGR5 expression correlates with SMAD2 expression." (PMID 29652830, 2018). "Recent studies have explored the potential prognostic value of a set of colorectal cancer stem cell markers—CD133, LGR5, ALDH1, CD44v6 and SOX2—investigated alone or in association with immune-related cell markers—CD3, CD8, Foxp3 and PD-L1—in 104 stage III colorectal cancer patients." (PMID 29652830, 2018). "To validate the effects of JIB-04 on the mRNA expression of β-catenin target genes, we measured the mRNA levels of CSC-associated genes (CD44, LGR5, DKK1, ALDH1A3, ALDH1B1, CD24, and SOX4) by qRT-PCR in three different colorectal cancer cell lines after treament with JIB-04." (PMID 29700375, 2018).
colorectal cancer (continued). "Moreover, increased expression of KDM1A is also associated with the expression of leucine-rich repeat-containing G-protein-coupled receptor 5 (LGR5), a well-known colorectal cancer stem cell marker." (PMID 29921310, 2018). "Colorectal cancers often exhibit aberrant activation of the Wnt/ βcatenin pathway leading to activation of downstream oncogenic targets, such as cyclin D1, c-Myc and the intestinal stem cell regulatory gene, Lgr5." (PMID 30197752, 2018). "Therefore, Lgr5 is considered an indicator of poor prognosis and a potential target of colorectal cancer." (PMID 30279970, 2018). "Indeed, Tie1‐positive tumor cells derived from a murine model overexpressed Lgr5, a typical stemness marker for colorectal cancer." (PMID 28464467, 2017). "Tie1‐positive tumor cells highly expressed Lgr5, a stemness marker for colorectal cancer." (PMID 28464467, 2017). "Furthermore, miR-363-3p was found to directly target and repress GATA6, which is a transcription factor enhancing the expression of LGR5 in colorectal cancer." (PMID 27816053, 2016). "Previously, LGR5 promoter hypermethylation was shown in colorectal cancer." (PMID 27409834, 2016). "As we know, differentiated cells aren’t capable of potent self-renewal and aresensitive to traditional chemotherapy drugs, so lgr5 methylation might enhance the chemotherapy that is sensitive to the colorectal cancer cell." (PMID 26599100, 2015). "Interestingly, we also observed that lgr5 was more frequently methylated in colorectal cancer colons than in normal colons, and that lgr5 expression was tightly regulated by methylation." (PMID 26599100, 2015). "Correlation of lgr5 methylation with clinicopathological features of colorectal cancer patients." (PMID 26599100, 2015). "We then determined whether salinomycin effectively reduced the expression of the main proposed markers of colorectal cancers stem cells, LGR5, CD133, CD44 and ALDH." (PMID 25565667, 2015). "In recent years, the overexpression of LGR5 has been observed in many types of cancers, including hepatocellular carcinoma, colorectal cancer, ovarian cancer, and basal cell carcinoma, suggesting that LGR5 may play an important role in tumorigenesis." (PMID 25193857, 2014). "They found the G protein-coupled receptor (lgr5) and intestinal stem cells signature gene (Ascl2) was expressed on mainly colorectal cancers, which supported the hypothesis that the cancer cells were derived from lgr5+/Ascl2+ crypt stem cells." (PMID 26056577, 2014). "Specifically, recent studies of colorectal carcinoma support the hypothesis that LGR5 is a marker of cancer stem cells in these tumors." (PMID 23596566, 2013). "In addition, in the case of colorectal carcinoma, LGR5 is expressed by a subpopulation of cells with stem cell-like properties (i.e., cancer stem cells or CSC)." (PMID 23596566, 2013). "In the present study, Lgr5 expression correlated with poor survival of colorectal cancer, indicating that Lgr5-positive cells may contain more CSCs." (PMID 23153436, 2012). "However, Walker and colleagues reported that LGR5 suppression in colorectal cancer cell lines induced increased invasion, growth and enhanced tumourigenicity." (PMID 22530031, 2012). "The combined detection of Lgr5 and Ki-67 expression, to some extent, may reflect the biological behavior of colorectal cancer." (PMID 23153436, 2012). "We aim to estimate the diagnostic performances of anterior gradient homolog-2 (AGR2) and Leucine-rich repeat-containing-G-protein-coupled receptor 5 (LGR5) in peripheral blood (PB) as mRNA biomarkers in colorectal cancer (CRC) and to explore their prognostic significance." (PMID 22605983, 2012). "In conclusion, Lgr5 is highly expressed in colorectal cancer cells." (PMID 23153436, 2012). "In order to determine whether Lgr5 is a potential marker of cancer stem cells, we investigated whether Lgr5 expression correlated with Ki-67 expression and prognosis in colorectal carcinoma." (PMID 23153436, 2012).
colorectal cancer (continued). "It was also found that Lgr5 is closed related to the worst prognosis of colorectal carcinoma." (PMID 23153436, 2012). "Thus LGR5 modulation has consistent and specific effects on the clonogenicity of colorectal cancer cell lines." (PMID 21829496, 2011). "This hypothesis needs to be directly investigated by co-staining a large set of primary colorectal cancer specimens, including the invasive front, for LGR5, β-catenin, wnt pathway target proteins and markers of cell adhesion or EMT." (PMID 21829496, 2011). "It is unclear, however, whether LGR5 upregulation in colorectal cancer cells contributes significantly to tumourigenesis through maintenance of colorectal CSC, or is simply a reflection of activated wnt signalling, with no direct functional role." (PMID 21829496, 2011). "Thus elevated levels of LGR5 in colorectal cancer cells are likely to be secondary to activated canonical wnt signalling, and mutations in β-catenin bypass the requirement for exogenous ligands." (PMID 21829496, 2011). "Thus the elevated expression of LGR5 in colorectal cancer is likely to be secondary to dysregulated wnt signalling." (PMID 21829496, 2011). "Additionally, LGR5 is a significant prognostic factor for colorectal cancer (CRC)." (PMID 41194856, 2025). "High LGR5 expression has also been significantly associated with poor overall survival (OS; HR, 1.87; 95% CI, 1.23–2.84; P = 0.003) and with worse disease-free survival (DFS; HR, 2.44; 95% CI, 1.49–3.98; P = 0.001) in the recently published colorectal cancer meta-analysis." (PMID 39225547, 2024). "In colorectal carcinoma (CRC), LGR5+ tumor cells have been proven to be the major CSC population, while metastatic sites are predominantly initiated by LGR5− cells." (PMID 39872661, 2024). "In another study about 5-Fu induced drug-resistant colorectal cancer cells, authors found that LGR5 + tumor cells were significantly enriched in pool of resistant cells by constructing an organoid model, which was similar to our analysis that LGR5 was highly expressed in radio-resistant cells." (PMID 37328854, 2023). "According to a 2022 report by McPeake and colleagues, LGR5-redirected CAR-Ts might be promising therapeutics for the treatment of colorectal cancer as administration of CNA3103 into preclinical mouse models mediated complete remission in all of the subjects (100%)." (PMID 38146364, 2023). "In colorectal cancer, the relationship between CSCs and cell plasticity was highlighted in lineage-tracing experiments using murine models where selective ablation of CSCs based on the intestinal stem cell marker leucine-rich repeat-containing G-protein coupled receptor 5 (Lgr5) was performed." (PMID 37894295, 2023). "Similarly, LGR5 has been identified as a target of the Wnt signaling pathway, essential in the maintenance of colon cancer stem cells, and its expression correlates with clinical outcomes in colorectal cancer." (PMID 38069256, 2023). "In colorectal cancer (CRC), RAC1 activation upon Apc loss triggers the production of high levels of ROS in the intestines of vil-Cre-ERT2 Apcfl/fl Rac1fl/fl mice; then, ROS further increase the expression of stemness genes (LGR5, OLFM4, RGMB), confer LGR5 CSC phenotypes, and thus initiate CRC." (PMID 37370081, 2023). "LGR5-GFP human colorectal carcinoma (CRC) cells as well as KRT20 (keratin 20)-GFP CRC cells were generated and permitted the formation of CRC organoids (COOs) in Matrigel." (PMID 34298613, 2021). "Furthermore, LGR5 is an established CSC marker in colorectal cancer." (PMID 32183251, 2020). "Furthermore, Lgr5 is required for the maintenance of spheroid-derived colorectal cancer cells." (PMID 30763370, 2019). "Indeed, systematic reviews and meta-analyses examining the significance of Lgr5 expression in tumors have shown that Lgr5 is a predictive factor for tumor invasion and metastasis, as well as an indicator of poor prognosis in gastric cancer (GC) and colorectal cancer (CRC)." (PMID 31417548, 2019).
colorectal cancer (continued). "Hence, the reappearance of Lgr5+ cells following complete elimination of the Lgr5+ colorectal cancers may result from the plasticity of Lgr5− colorectal cancers and the transition between Lgr5+ CSCs and Lgr5− CSCs." (PMID 31358061, 2019). "Lineage‐tracing experiments have shown that the leucine‐rich repeat‐containing G‐protein‐coupled receptor‐5‐positive (Lgr5+) intestinal stem cells, which normally reside at the bottom of the intestinal crypt, are the cells of origin of intestinal adenomas, the precursors of colorectal cancer." (PMID 31545551, 2019). "Recently, some studies show that Lgr5 is a marker of stem cells in small intestine and colon and cancer stem-like cells of colorectal carcinoma (CRC), and its over-expression is also detectable in CRC." (PMID 30046385, 2018). "Leucine-rich repeat-containing G-protein-coupled receptor 5 (Lgr5) is a downstream target gene of the Wnt/β-catenin signaling pathway and identified as a marker of cancer stem-like cells of colorectal carcinoma (CRC)." (PMID 30046385, 2018). "Different studies have pinpointed the parallelisms between mouse and human colorectal cancer at epigenetic level and many of the genes we have found hypermethylated in early stages of mouse tumorigenesis (i.e., Lgr5, Axin2 and En1) may have potential clinical applications in human cancer." (PMID 25933092, 2015). "However, one recent report showed that suppression of LGR5 expression in colorectal cancer cells enhanced tumor formation with increased cell motility, while cells overexpressing LGR5 tended to grow with tight cell-to-cell contact and exhibited reduced cell motility." (PMID 24172981, 2014). "Moreover, in humans, Lgr5 is a selective marker for human colorectal cancer stem cells." (PMID 24920319, 2014). "Additionally, LGR5 has been recognized as a cancer stem cell marker for colorectal cancers." (PMID 25193857, 2014). "In addition to CD133, CD44, EpCAM, and CD166, the expression of leucine-rich repeat-containing G-protein-coupled receptor 5 (Lgr5) varies among colorectal cancer (CRC) cases and is significantly correlated with lymphatic and vascular invasion, lymph node metastasis, and drug resistance." (PMID 24427168, 2014). "Therefore, LGR5- positive cells are thought to represent candidates for CSCs of colorectal cancer." (PMID 24133453, 2013). "Thus Lgr5 may be a potential new therapeutic target for the treatment of colorectal cancer patients, particularly those with advanced colorectal cancer." (PMID 23153436, 2012). "Furthermore, Lgr5 was seen more frequently in advanced colorectal cancer." (PMID 23153436, 2012). "Since a decrease in LGR5 levels specifically enhances the clonogenicity of colorectal cancer cell lines, we investigated whether LGR5 overexpression would reduce the growth of these cells in soft-agar by performing both transient and stable overexpression of LGR5 in colorectal cell lines." (PMID 21829496, 2011). "Mouse models show that LGR5+ cells are the cells of origin of intestinal cancer, and LGR5 expression is elevated in human colorectal cancers, however very little is known about LGR5 function or its contribution to the stem cell phenotype and to colorectal cancer." (PMID 21829496, 2011). "The relationship between drug-tolerant residual cancer cells and cancer stem cell (CSC) properties has attracted attention, with the presence of CSC markers such as LGR5- and CD44-positive cells being reported in colorectal cancer." (PMID 40537472, 2025). "LGR5 has been widely studied in colorectal cancer (CRC) and the majority of studies have shown that high LGR5 protein expression is related to poor survival outcome." (PMID 39821694, 2025). "Colorectal cancer (CRC) tumors are composed of heterogeneous and plastic cell populations, including a pool of cancer stem cells that express LGR5." (PMID 38637494, 2024).
colorectal cancer (continued). "The dysregulation of the Wnt signaling pathway and a high-fat diet in colorectal cancer lead to alterations in bile acid distribution, activation of FXR, and subsequent malignant transformation of the Lgr5+ subpopulation of CSCs." (PMID 38994204, 2024). "Our data suggest that LGR5, KCNN4, TNS4 and CENPH are correlated with radiation sensitivity of colorectal cancer cells, and the indicator composed by them can reflect the prognosis of colorectal cancer patients undergoing radiation therapy." (PMID 37328854, 2023). "Motivated by the role of CSCs in chemoresistance, we quantified the expression of several prominent CSC gene markers in colorectal cancer, i.e., ALDH1A3, CD166, CD133, and LGR5, following each cycle of treatment." (PMID 37791907, 2023). "Proteins have been proposed as colorectal cancer stem cell markers, including CD133, CD44, ALDH1A1, LGR5 and several others, and these proteins are considered prognostic indicators of CRC." (PMID 34148069, 2021). "Using CRISPR-Cas9 approach, inducible caspase 9 (iCasp9) was inserted in the LGR5 locus of human colorectal cancer organoids, which is a common CSC marker for colorectal cancer." (PMID 33505918, 2020). "In colorectal cancer, a high-fat diet and dysregulated WNT signalling pathway alter bile acids profiles, activate FXR, and drive malignant transformation in Lgr5+ subpopulation CSCs, which promote an adenoma-to- adenocarcinoma progression." (PMID 32641978, 2020). "The colorectal cancer cells that undergo EMT exhibit properties of EMT and CSCs, such as high expression of Snail, Lgr5, CD133, CD44 and EpCAM." (PMID 30279970, 2018). "A recent study was particularly instructive, showing the variability of the optimal ROI to be analyzed for five different colorectal cancer stem cell markers (ALDH1, CD44v6, CD133, LGR5 and SOX2)." (PMID 29652830, 2018). "Using the HT29 transplantation model, we assessed the expression of Lgr5, CD44, and CD133, major human colorectal cancer stem cell markers 25, and CK20, a characteristic differentiation marker 26 by sorted Tie1‐positive cancer cells." (PMID 28464467, 2017). "Colorectal cancer stem cells (CSCs) are responsible for the initiation, progression and metastasis of human colorectal cancers, and have been characterized by the expression of cell surface markers, such as CD44, CD133, CD166 and LGR5." (PMID 29064439, 2017). "As proof of concept, we engineered human colorectal cancer (CRC) organoids that carry EGFP and lineage‐tracing cassettes knocked in the LGR5 locus." (PMID 28468934, 2017). "Multiple antibodies directed against LGR5 (Sigma-Aldrich, HPA012530; Abgent, AP2745; Abcam, ab75850), CD44 (Abcam, ab41478) and EPHB2 (R&D, AF467) were tested on normal human colon and colorectal cancer tissues." (PMID 26367378, 2015). "For colorectal cancer, several CSC markers have been identified, including CD133, Epcam/CD44/CD166, CD24/CD29 and lgr5." (PMID 26599100, 2015). "Additionally, Lgr5 may also predict chemotherapy response in colorectal cancer." (PMID 24666414, 2014). "Several colorectal cancer CSC markers have been reported to date, including CD133, CD44, CD24, CD166, and Lgr-5." (PMID 25396735, 2014). "The cell surface receptor leucine-rich repeat-containing G-protein coupled receptor 5 (LGR5) is a somatic stem cell marker that functions as an oncogene in several human cancers, most notably colorectal carcinoma." (PMID 23596566, 2013). "Indeed, amongst a panel of five additional colorectal cancer cell lines (HCT116, SW480, RKO, DLD1 and HT29), LoVo cells were amongst the higher LGR5 transcript and protein expressors." (PMID 39169164, 2024).